EGR1 (early growth response 1)
Diseases named in the same sentence as EGR1 in open-access papers (continued):
Sharing a sentence is not in itself a finding about the gene and the disease.
breast carcinoma (continued). "In breast cancer, the interaction of TBX2 with EGR1 represses the putative breast tumor suppressor, NDRG1 (N-myc downregulated gene 1), which is implicated in cell differentiation, apoptosis and senescence." (PMID 29719592, 2018). "Thus, EGR1 levels in breast cancer cells may be closely regulated by a functional ER pathway." (PMID 29228577, 2017). "In this context, EGR1 represents a good candidate based on its ability to increase TTP expression in breast cancer cells and HDAC inhibitors can induce EGR1 expression." (PMID 26343742, 2015). "To further establish the relationship between EGR1 and miR-20b expression in a large amount of breast tissue samples, we performed immunohistochemical and FISH analyses of EGR1 and miR-20b on breast cancer tissue arrays." (PMID 23945289, 2013). "Specific pharmacological inhibitors and gene-silencing procedures were used to show that BPA induces the expression of the GPER target genes c-FOS, EGR-1, and CTGF through the GPER/EGFR/ERK transduction pathway in SKBR3 breast cancer cells and CAFs." (PMID 22552965, 2012). "EGR1 and EGR2 directly regulate a series of classical tumor suppressors, and experimental interference of their expression dramatically alter breast cancer cell growth rates." (PMID 21627793, 2011). "Expression levels of BDNF and BDNF-correlated genes CCND2, DUSP6, EGR1, KLF10 and PTPRF are altered in breast cancer." (PMID 19737418, 2009). "Knockdown of PLCH1 using two specific siRNAs (si-PLCH1#1 and si-PLCH1#3) in BT-474 breast cancer cells significantly reduced the expression of p-ERK and early growth response 1 (EGR1), key components of the ERK signaling pathway, as demonstrated by Western blot analysis." (PMID 40519297, 2025). "In the same way, in breast cancer, pathway analysis emphasized the role of extracellular matrix disassembly, hormone metabolism, and angiogenesis, where the major players were genes such as MMP11 (facilitating metastasis) and EGR1 (tumor suppressor)." (PMID 40565055, 2025). "NR4A1, PSMC1, and EGR1 were selected as MIDN-interacted proteins, and these four molecules were co-expressed in pancreatic cancer, liver cancer, urothelial cancer, melanoma, and breast cancer." (PMID 40002690, 2025). "EGR1 regulated KLF4 and vasculogenic expression in aggressive MDA-MB-231 breast cancer cells." (PMID 37762678, 2023). "They found that CTCF and early growth response 1 (EGR1) could regulate Nm23-H1 gene expression, thereby controlling breast cancer cell metastasis." (PMID 35509102, 2022). "used breast cancer cells (MDA-MB-231, SUM159, BT-574) and found that DMOCPTL directly bound to the glutathione peroxidase 4 (GPX4) to up-regulate early growth response 1 (EGR1) in TNBC cells, leading to apoptosis of mitochondrial mediator and further inhibiting breast tumor growth." (PMID 36568247, 2022). "One study has reported that EGR1 could localize to the NDRG1 proximal promotor and regulate cell proliferation and survival in breast cancer." (PMID 35982887, 2022). "Moreover, miR-29a promotes breast cancer EMT via attenuating the repression of connective tissue growth factor (CTGF) and early growth response protein 1 (EGR1) by H4K20 trimethylation." (PMID 33413418, 2021). "Simultaneously, the key genes, including ZFP36, EGR1, and FOS may be potentially effective targets of BD and also are crucial for breast cancer development." (PMID 32714860, 2020). "Hence, we attempted to explore the potential mechanism capable of explaining why higher expression levels of EGR1, EGR2, and EGR3 predicted better outcomes in patients with breast cancer." (PMID 33614706, 2020). "Furthermore, we discovered that SUV420H2-targeting miR-29a attenuated the repression of connective tissue growth factor (CTGF) and growth response protein-1 (EGR1) by H4K20 trimethylation and promoted the EMT progress of breast cancer cells." (PMID 30792382, 2019).
breast carcinoma (continued). "Our data support the finding that EGR1 could serve as oncogene in the breast cancer and first provide the evidence that it links to EGF, ERK, EGR1, PN-1 and cell migration." (PMID 31501409, 2019). "This ssDNA was successfully delivered into MCF-7 human breast cancer cells by nanocrystals of Ni-IRMOF-74-II, in which it was released by pairing up with target mRNA, thus inhibit the expression of EGR-1 gene with nearly 76% inhibition efficiency." (PMID 29615605, 2018). "Finally, EGR1 and ESR1 mRNA abundance were strongly and negatively correlated in ER+ breast cancers analyzed using TCGA (Pearson’s R = -0.21; p = 2.7e-10)." (PMID 29614078, 2018). "We describe that SGK1 regulates the expression of NDRG1 via regulation of expression of EGR1, a transcription factor from the AP-1 network genes, in breast cancer independent of the PR status of cells." (PMID 30337371, 2018). "In addition, miR-152 plays an important role in breast cancer cell proliferation and angiogenesis via PKM2/NF-κB/EGR1/miR-152 complex in respond to IGF-1R activation." (PMID 29162853, 2017). "Contrarily, EGR1 expression is often absent or reduced in breast cancer, which also results in tumor growth." (PMID 29246166, 2017). "Overexpression of Cul5 in T47D breast cancer cells decreases cell growth and mitogen activated protein kinase (MAPK) phosphorylation, and Cul5 overexpression downregulates early growth response 1 (EGR-1) protein expression and upregulates Fas-L mRNA expression." (PMID 27030794, 2016). "In breast cancer, fibrosarcoma, and MDS, Egr-1 has been described as a tumor suppressor." (PMID 26136341, 2015). "Furthermore, we detected upregulation of genes that are downregulated in the primaries of breast cancer patients, including c-FOS, EGR1 and ID2." (PMID 24980816, 2014). "In addition, transcription factors known as tumor suppressors or genes related to breast cancer including c-FOS, EGR1, ID2 and SERPINB2, as well as suppression of metastasis associated genes (CD44 and IL11) have emerged as molecular targets of BSP knockdown." (PMID 24980816, 2014). "EGR1 was upregulated in 40% breast cancer tissues, and miR-20b was elevated in 30% breast cancer tissues examined: upregulated EGR1 correlated significantly with upregulated miR-20b in the normal, benign, and tumor tissues tested (r=0.99, p=0.032)." (PMID 23945289, 2013). "The genes belonged to a variety of biological functions such as cell motility and invasion (Cdc42, ITGB2), cell cycle (EGR1, RRM2) or signal transduction (VEGFC), indicating that expression of E-cadh and P-cadh in breast cancer cells have a significant impact on their overall genetic program." (PMID 19257890, 2009). "Therefore, we hypothesized that FOS, FOSB, EGR1, and EGR3 mainly function as tumor suppressor genes to inhibit the occurrence and progression of breast cancers." (PMID 37233869, 2023). "In addition to EGR1, CD63 and BIRC3 were also found to be associated with breast cancer, while USF2′s role in breast cancer has not been clearly investigated." (PMID 34252628, 2021). "As another example, scLink identified an edge between EGR1 and NUDT3 in the normal sample (scLink’s correlation = − 0.48, adjusted P = 0.004) but not in the tumor sample (scLink’s correlation = 0.35), and both genes were reported to have regulatory roles in breast cancer." (PMID 34252628, 2021). "Although the role of CTCF and EGR1 in breast cancer cell proliferation are more well-established as compared to their functions in metastasis, this study supports metastasis suppressor roles for CTCF and EGR1 in breast cancer by acting as positive regulators of NME1 transcription." (PMID 33436746, 2021). "The results showed BD in breast cancer treatment may take actions through affecting AMIT_SERUM_RESPONSE_40_MCF10A, BILD_HRAS_ONCOGENIC_SIGNATURE, and NAGASHIMA_NRG1_SIGNALING_UP pathways and regulation expression of ZFP36, EGR1, and FOS(c-FOS)." (PMID 32714860, 2020).
breast carcinoma (continued). "At three concentration of BD, 0.1, 0.5, and 1.5 μM, the expression of ZFP36 and EGR1 mRNA were increased in MCF-7 and MDA-MB-231 cells in a dose-dependent manner, while the level of FOS mRNA was significantly reduced in a concentration-dependent manner in MCF-7 and MDA-MB-231 breast cancer cells." (PMID 32714860, 2020). "In conclusion, these findings revealed potential molecular mechanisms of BD to treat breast cancer by affecting AMIT_SERUM_RESPONSE_40_MCF10A, BILD_HRAS_ONCOGENIC_SIGNATURE, and NAGASHIMA_NRG1_SIGNALING_UP pathways and regulating expression of ZFP36, EGR1, and FOS." (PMID 32714860, 2020). "We confirmed EGR1, FOS and EPOR as transcription targets of the EPO-EPOR signaling loop, but could not correlate the expression of different EPOR isoforms with the invasiveness of breast cancer cell lines." (PMID 24294184, 2013). "In human breast cancer cells, GPR30 was found to be necessary for BPA-induced activation of Erk1/2, cell proliferation and migration, and transcriptional regulation of genes (c-fos, EGR-1, and CTGF) independent of ERα/β-mediated signaling." (PMID 34831106, 2021).
prostate carcinoma (93 papers, 2002 to 2025). A carcinoma that arises from epithelial cells of the prostate gland. "In summary, our study illustrated the association between HnRNP-L, circCSPP1, miR-520h, and EGR1 in prostate cancer and the potential underlying mechanism to promote malignancy." (PMID 34760337, 2021). "The tumorigenic role of EGR1 was first revealed in prostate cancer where Egr1-deficient mice showed impaired tumorigenesis rate." (PMID 34409922, 2021). "Further investigation is warranted to identify other important autophagy-associated genes regulated by EGR1 in prostate cancer." (PMID 34760337, 2021). "Under hypoxic conditions, EGR1 expression in prostate cancer cells increases, and EGR1 directly binds to the HIF1 promoter, causes HIF1 expression, and contributes to tumor angiogenesis." (PMID 33842351, 2021). "EGR1 was also reported to promote prostate cancer bone and brain metastasis, as demonstrated by the reduction of blood vessel density in brain and bone caused by decreased EGR1 expression." (PMID 32974202, 2020). "As discussed in the previous paragraph, the transcription factor EGR-1 has been shown to associate with the promoter of hPar1 in prostate cancer, leading to hPar1 overexpression and enhancement of invasive properties." (PMID 30400241, 2018). "Egr1 also regulates IL8 in the DU145 prostate cancer cell line, as Egr1 shRNA caused a decrease in IL8 transcription and production." (PMID 23342084, 2013). "Egr-1 has been shown to regulate the transformation to invasive carcinoma in prostate cancer tumorigenesis, where Egr-1 deficient mice display impaired tumorigenesis." (PMID 19878561, 2009). "Another study examined tumor development in mice genetically predisposed to prostate cancer that had been crossed with Egr-1-/- mice." (PMID 19200397, 2009). "Finally, we verified the association among the circCSPP1/miR-520h/EGR1 axis in both our prostate cancer samples and cancerous xenografts." (PMID 34760337, 2021). "Bioinformatics analysis indicated that circCSPP1 can interfere with the complementary binding between miR-520h and early growth response factor 1 (EGR1), a well-known oncogene that causes tumorigenesis and metastasis in prostate cancer through the regulation of cell autophagy." (PMID 34760337, 2021). "Interestingly, EGR1 expression is correlated with prostate cancer progression and promotes prostate cancer metastases, which are associated with a massive increase of matrix." (PMID 32121305, 2020). "However, the tumor-suppressive role of EGR1 seems to be tissue specific, because several studies implicated a tumor growth-promoting role of EGR1 in prostate cancer progression." (PMID 23505378, 2013). "Moreover, Egr1 is a key transcription factor implicated in the development and progression of prostate cancer." (PMID 20565877, 2010). "Gene expression profiling in human prostate cancer tissue was probed utilizing EGR1 expression techniques and RNA‐sequence analysis." (PMID 40078339, 2025). "EGR1 expression correlates with the progression of several cancers, including prostate cancer and gastric cancer, and it is involved in proliferation, apoptosis, and matrix degradation." (PMID 40190348, 2025). "EGR1 plays an important role in cancer by promoting tumorigenesis through enhanced cyclin D1 expression in prostate cancer and by interacting with vascular endothelial growth factor A (VEGFA) to stimulate angiogenesis in lung cancer." (PMID 41561975, 2025). "In prostate cancer, siRNA downregulation of EGR1 expression inhibited the growth of the human prostate cancer cell line PC-3." (PMID 38408959, 2024). "EGR1 expression was elevated in gastric cancer, prostate cancer, and glioblastoma compared to normal tissues." (PMID 38244586, 2024).
prostate carcinoma (continued). "EGR1 is overexpressed in prostate cancer, while NAB2 expression is reduced in most prostate cancer samples, which suggest that repression of EGR1 activity promote prostate cancer." (PMID 36979412, 2023). "Consistent with our findings, the upregulation and nuclear translocation of Egr1 has also been shown to induce cell death in prostate cancer cells." (PMID 38248651, 2023). "Upregulation of EGR-1 and loss of its repressor NAB2 contribute to increasing levels of EGR-1 activity in prostate cancer." (PMID 36233659, 2022). "In our study, we develop and validate a prognostic signature (named TILTregSig) composed of five Treg-specific mRNAs (SOCS2, EGR1, RRM2, TPP1, and C11orf54) for prostate cancer, which is associated with RFS in prostate cancer." (PMID 35812443, 2022). "The NAB2 (NGF-1A binding protein), which represses the transcriptional activity of EGR-1, is down-regulated in prostate carcinomas." (PMID 36233659, 2022). "EGR1 is a transcription factor involved in the regulation of cell proliferation and apoptosis, and it is evident that EGR1 promotes the development of prostate cancer." (PMID 35046398, 2022). "In prostate cancer, EGR-1 expression was significantly increased in tumors with Gleason scores of 8–10." (PMID 36233659, 2022). "In prostate cancer, EGR1 induces TGFβ1 expression which stimulates tumor tissue growth and angiogenesis." (PMID 35906698, 2022). "The tumorigenic role of EGR-1 has been first revealed in prostate cancer, where high expression of EGR1 triggered cell proliferation and metastasis, leaving EGR1 as a candidate target for the therapy of prostate cancer." (PMID 34409922, 2021). "The activated MAPK pathway enhanced the interaction of EGR1 and cyclin D1, and then increased the cyclin D1 protein level in prostate cancer cells." (PMID 34681812, 2021). "We also implemented qRT-PCR to verify the expression of circCSPP1, miR-520h, and EGR1 both in prostate cancer tissues and benign tissues." (PMID 34760337, 2021). "Then we examined the expression of EGR1 in prostate cancer cell lines with the transfection of miR-520h mimics." (PMID 34760337, 2021). "The results revealed that overexpression of EGR1 significantly promoted the proliferation, migration, and invasion in prostate cancer cells." (PMID 34760337, 2021). "The results showed that the expression levels of both circCSPP1 and EGR1 were higher in the prostate cancer tissues than in the benign tissues, whereas the expression of miR-520h was lower in prostate cancer tissues than that in benign tissues." (PMID 34760337, 2021). "It was reported that EGR1 expression was required for the osteocyte-derived GDF15-mediated induction of in vitro prostate cancer cell proliferation, migration and invasion." (PMID 34681812, 2021). "Overexpression of HnRNP-L upregulates the circCSPP1/miR-520h/EGR1 axis, then inducing autophagy and eventually accelerating prostate carcinoma progression." (PMID 34760337, 2021). "In prostate cancer, Egr1 inhibits IL-8-mediated invasion of prostate cancer cells through suppressing the Egr1/NF-κB pathway." (PMID 31399076, 2019). "EGR1 overexpression is well correlated with the loss of its co-repressor NAB2 in primary prostate carcinoma; this unbalance between EGR1 and NAB2 expression results in high EGR1 transcriptional activity in prostate carcinoma cells." (PMID 30925677, 2019). "Egr-1 is upregulated in primary human prostate carcinomas and in numerous downstream Egr-1 genes (e.g., transforming growth factor β1, insulin-like growth factor II, and platelet-derived growth factor A-chain), that have been connected to prostate cancer." (PMID 30400241, 2018). "High levels of EGR1 mRNA expression was seen in prostate cancer tissue compared to normal tissue and blocking EGR1 expression in prostate tumor cell lines showed a decrease in cell proliferation and reversion of the transformed phenotype." (PMID 29719592, 2018).